IL6 (interleukin 6)
Diseases named in the same sentence as IL6 in open-access papers (continued):
Sharing a sentence is not in itself a finding about the gene and the disease.
colorectal cancer (continued). "Our present results suggest the essential role of IL-6/STAT3/miR-92a/Wnt/β-catenin pathway in regulating the stem cell-like traits of colorectal cancer cells and provide a potential target for colorectal cancer therapy." (PMID 29254202, 2017). "Collectively, RAB3C upregulation facilitates colorectal cancer metastasis by promoting IL-6 secretion and recruiting members of the STAT3-related pathway." (PMID 28784136, 2017). "It should to be noted that the expression of proinflammatory cytokines such as IL-17A, IL-6, IL-22 was dramatically increased in lesions of colorectal cancer and their high expression significantly correlated with cancer progression and poor prognosis." (PMID 28811578, 2017). "We found that using interleukin 6 to induce p-STAT3 activation in colorectal cancer cell lines can result in vasculogenic mimicry and using AG490 to suppress p-STAT3 activation restrained vasculogenic mimicry." (PMID 29333928, 2017). "In conclusion, increased RAB3C expression is correlated with poor prognosis and distant metastasis in colorectal cancer patients and regulates exocytosis and IL-6 secretion." (PMID 28784136, 2017). "IL-6 is part of a central pathway in the pathogenesis of chronic inflammation diseases, such as IBD, and inflammation-associated colorectal cancer." (PMID 27801847, 2016). "The correlations of pretreatment serum concentrations of proinflammatory cytokines such as interleukin (IL)‐1β, IL‐6, and tumor necrosis factor‐α (TNFα) with the clinicopathologic features and progression of colorectal cancer (CRC) were investigated." (PMID 26799163, 2016). "Consistent with the present finding, cytoplasmic staining pattern for IL-6 expression was also observed in ovarian cancer, renal cell carcinoma, colorectal cancer, and gastric cancer." (PMID 27034885, 2016). "Contradictory to this, IL-6 expression has been found to be significantly associated with poor prognosis in OSCC patients, esophageal squamous cell carcinoma, colorectal cancer, and ovarian cancer." (PMID 27034885, 2016). "By using immunohistochemistry, western blot, and ELISA, we found in this study that IL-6 is upregulated in colorectal carcinoma especially in low grade carcinoma, accompanied with enhanced STAT3 activation." (PMID 27006530, 2016). "The activation of IL-6/STAT3 axis has been associated with chemoresistance and poor prognosis of a variety of cancers including colorectal carcinoma and thus serves as a potential immunotherapeutic target for cancer treatment." (PMID 27006530, 2016). "Finding the colorectal cancer cell growth-promoting activity of IL-6 agrees with the literature data, which additionally indicate that this cytokine exerts its effects via transsignaling, in particular involving the activation of STAT3." (PMID 26284488, 2015). "Apart from the stimulation of colorectal cancer cell proliferation, IL-6 has also been recognized as a molecule contributing to cancer cell invasiveness." (PMID 26284488, 2015). "IL-6 and IL-23 have been found in various tumors, including prostate and ovarian tumors as well as colorectal cancers and other malignancies." (PMID 26684834, 2015). "The literature evidence regarding the association of circulating concentrations of inflammatory biomarkers, other than CRP, IL-6, and TNF-α, and the risk of colorectal cancer is very sparse." (PMID 26321888, 2015). "Taking the previous findings into consideration, a high G/L ratio prior to surgery in patients with colorectal cancer indicates high pre-operative IL-6 levels, i.e., a biological invasion, which is believed to cause post-operative complications." (PMID 25436003, 2015). "Colorectal cancer patients had increased serum levels of IL-6, IL-1beta, TNF-alpha, and IL-8 but lower IL-10 concentrations." (PMID 26300773, 2015). "This study provides further support for inhibiting IL-6 trans-signaling as a clinical therapeutic strategy for colorectal cancer." (PMID 26673628, 2015).
colorectal cancer (continued). "Based on these observations, we treated colorectal cancer cells with IL-6 to induce them to become more invasive and metastatic." (PMID 26258407, 2015). "IL6 is a key mediator in a mouse model of microbially induced colorectal cancer, possibly through induction of cancer-related molecular pathways such as those involving STAT3." (PMID 24885802, 2014). "A similar result was obtained from the human colorectal carcinoma cell in which the IL-6 expression level of the 3M002-treated cell was higher than that in the untreated cell (data not shown)." (PMID 25547486, 2014). "Studies suggesting that circulating levels of IL-6 and TNF-α are associated with colorectal cancer are fairly consistent." (PMID 24235998, 2013). "Intriguingly, some data suggest that the interaction of MSCs and colorectal cancer cells stimulates the production of IL-6 by MSCs, which induces cancer stem cell formation and recruits endothelial cells to the tumor sites." (PMID 23977098, 2013). "The ApcMin/+ mouse is an established colorectal cancer model that develops an IL-6 dependent cachexia which is physiologically related to human disease due to the gradual progression of tumor development and cachexia." (PMID 24285707, 2013). "The proinflammatory cytokines IL-6 and IL-8 are known to be involved in the development of colorectal cancer." (PMID 22848630, 2012). "Increased IL6 expression has therefore been proposed as a clinically relevant factor for poor prognosis in patients with a number of cancers, including colorectal cancer, non-small cell lung cancer, Hodgkin’s lymphoma, and renal cell carcinoma." (PMID 23185547, 2012). "In fact, within our colorectal cancer patient group we noted alterations in the IFNγ pathways in men and IL-6 in women and persistence of IL-10 under both resting and activated conditions." (PMID 22235223, 2011). "The ApcMin/+ mouse is a model of colorectal cancer that develops cachexia that is dependent on circulating IL-6." (PMID 21949739, 2011). "This work was aimed at studying the clinical relevance of serum vascular endothelial growth factor (VEGF) and interleukin -6 (IL-6), in patients with colorectal cancer (CRC)." (PMID 21546718, 2011). "Clinically, serum IL-6 levels increase in colorectal cancer patients relative to healthy controls, and is correlated with tumour size, suggesting its potential as a prognostic marker of tumour progression." (PMID 20823887, 2010). "In a previous study, we found that IL-1β stimulation induced IL-6 production in colorectal cancer cells, which was counteracted by IL-1RA, suggesting that IL-1RA inhibits the IL-1/IL-6 cascade in colorectal cancer cells." (PMID 20823887, 2010). "High serum CRP concentrations have been correlated with elevated IL-6 serum concentrations and with poor prognosis in solid tumours such as colorectal cancer and with mortality in RCC." (PMID 20808314, 2010). "We also examined the significance of IL-6 trans-signalling in the cancer microenvironment with colorectal cancer progression." (PMID 20823887, 2010). "Many cancer cells produce interleukin-6 (IL-6), a cytokine that plays a role in growth stimulation, metastasis, and angiogenesis of secondary tumours in a variety of malignancies, including colorectal cancer." (PMID 18205904, 2008). "In colorectal cancer, it has been reported that interleukin-6 concentrations increase with tumour stage and correlate with CEA concentrations." (PMID 15700032, 2005). "In cervical, ovarian and colorectal cancer IL-6 is shed in the blood by the tumour, creating a 2.5-fold arteriovenous gradient." (PMID 15743502, 2005). "All patients with colorectal cancer had extensive IL-6 labelling in the tumour cell compartment (n=14)." (PMID 12454774, 2002). "Both molecules are associated with colorectal cancer progression, where SPP1 might promote cancer cell migration and invasion and where IL6 is a pro-inflammatory cytokine that may promote cancer cell proliferation and survival." (PMID 40895532, 2025).
colorectal cancer (continued). "IL-1β and IL-6 are important cytokines for both intestinal inflammation and colorectal cancer." (PMID 40002819, 2025). "On the one hand, they can significantly inhibit NF-κ B/p65 signaling pathway activity, thereby down-regulating IL-6, TNF-α and IL-1β and up-regulating IL-10 in the serum of patients with colorectal cancer, which further reduces the inflammatory response associated with colorectal cancer." (PMID 40520902, 2025). "Furthermore, increased serum IL-6 levels have been correlated with larger tumor sizes and a higher likelihood of metastasis in colorectal cancer." (PMID 40141426, 2025). "Elevated IL6 levels were found in serum and tumor tissue of patients with colorectal cancer." (PMID 41209739, 2025). "This suggests that IL-6 is essential in naringenin inhibition of colorectal cancer." (PMID 40295196, 2025). "This study evaluated esketamine's effects on serum biomarkers of oxidative stress (glutathione, catalase, malondialdehyde, superoxide dismutase), inflammatory mediators (TNF-a, CRP IL-6), and T lymphocyte subsets in patients undergoing laparoscopic colorectal cancer resection." (PMID 40951888, 2025). "Additionally, elevated serum levels of IL-6 have been shown to correlate with more advanced stages of colorectal cancer, highlighting its significant role in disease progression." (PMID 41256010, 2025). "Moreover, the mRNA of this protein was reported to be down-regulated in colorectal cancer and its abrogation led to the promotion of tumorigenesis as well as the up-regulation of IL-6." (PMID 41462636, 2025). "IL-6 has been implicated as mediator of tumor progression and chemoresistance in multiple cancers such as NSCLC and colorectal cancer wherein IL-6 has been observed to modulate autophagy by inducing phosphorylation of BECN1 via the IL-6/JAK2/BECN1 signaling pathway." (PMID 40176914, 2025). "For example, a colorectal cancer mouse model demonstrated that IL‐6 signaling induced EMT." (PMID 40985344, 2025). "Reducing IL-6 and TNF-α expression and infiltration of pro-inflammatory macrophages, remodeling gut microbiota composition and bile acid metabolism to inhibit the TLR4/MyD 88 pathway, and thereby inhibiting colorectal cancer associated with a high-fat diet." (PMID 40066456, 2025). "In colorectal cancer, iCAFs enhance chemotherapeutic resistance by producing IL-6 and CXCL12." (PMID 41408647, 2025). "This organ protection measure in patients undergoing laparoscopic colorectal cancer resection decreased the incidence of postoperative gastrointestinal dysfunction and lowered the IL-6, TNF-α, and I-FABP levels, demonstrating protective effect on patients’ postoperative gastrointestinal function." (PMID 39202020, 2024). "Moreover, some authors reported that IL-6 modulates CLU expression in colorectal cancer, which can also be applied to the pathogenesis of other inflammatory diseases, including RA." (PMID 39684771, 2024). "Interestingly, IL6 modulates the TIME to facilitate metastatic colonization of colorectal cancer cells." (PMID 39408697, 2024). "Furthermore, IL6 plays a fundamental role in detecting and differentiating tumor cells, including colorectal cancer (CRC) cells." (PMID 39432122, 2024). "This suggests that therapeutic inhibition of IL-6 and IL-11 signalling via inhibition of the gp130 receptor could be a beneficial treatment option for colorectal cancer patients." (PMID 38600086, 2024). "In colorectal cancer, for example, IL-6 signalling via STAT3 results in repression of a micro-RNA (miR-34a), that in turn results in increased expression of EMT signature genes associated with invasion and metastasis, such as vimentin, SNAIL, SLUG and ZEB1, with concommitant loss of E-cadherin." (PMID 38689325, 2024). "Our data in an in vitro mouse colorectal cancer model on the MC38 cell line show the dasatinib/quercetin combination to successfully eliminate senescent CAFs alongside a significant elevation in secretory IL-6 levels." (PMID 38612842, 2024).
colorectal cancer (continued). "In a clinical trial on 47 colorectal cancer patients, several immune parameters such as IL‐1, IL‐6, IFN‐γ, CD3 and CD4 were altered after 12 weeks of oral administration of G. lucidum, suggesting that it may be helpful in modulating tumour immunity." (PMID 38451046, 2024). "Furthermore, in colorectal cancer, IL-6 produced by TAMs activates the STAT3 pathway and consequently blocks expression of the miR-204-5p tumor suppressor." (PMID 38280079, 2024). "IL-6 is highly upregulated in animal models of colorectal cancer." (PMID 38540292, 2024). "Additionally, MTERF3 was reported to promote cell growth and irradiation resistance by regulating interleukin (IL)-6 and IL-11 in colorectal cancer cells." (PMID 38397465, 2024). "Satoshi found that circulating IL6 levels are associated with the survival rate of colorectal cancer patients, indicating that IL6 may be a potential target for the treatment of colorectal cancer." (PMID 38961677, 2024). "Intriguingly, recombinant human IL-6 stimulated SIX4 expression in colorectal cancer cell lines." (PMID 39309424, 2024). "Moreover, the overexpression of LOX in colorectal cancer cells triggers the production of interleukin-6 (IL-6), which in turn activates the signal transducer and activator of transcription 3 (STAT3) signalling pathway." (PMID 39247609, 2024). "Finally, IL‐6 has been reported to be a crucial tumor‐promoting cytokine with expression significantly increased in colorectal carcinoma." (PMID 38886975, 2024). "Furthermore, as part of the interactions among inflammatory cytokines, TNF, as such a mediator, can induce IL-6 expression in colorectal carcinomas, inducing therapeutic benefits in CRC clinical trials through IL-6 inhibition and anti-TNF therapies." (PMID 38338927, 2024). "Moreover, a study demonstrated that bradykinin mediated the migration and invasion of colorectal cancer by inducing IL-6 production." (PMID 37627528, 2023). "IL-6 also participates in tumour spreading and metastasis formation in colorectal cancer." (PMID 38098074, 2023). "IL-6 plays an important role in the metastasis and progression of colorectal cancer." (PMID 36983320, 2023). "Similarly, in a study using a murine model of colorectal cancer, the administration of the probiotic Bifidobacterium longum was correlated with an increase in miR-145 and a decrease in IL-6 concentration." (PMID 37834058, 2023). "Furthermore, the formation of CIC structures was increased in colorectal cancer tissues treated with high concentrations of the inflammatory mediator IL-6 compared to those treated with low concentrations of IL-6." (PMID 37790755, 2023). "The study also discovered that Alistipes could promote the development of colorectal cancer through activation of the interleukin-6/signal transducer and activator of transcription 3 signaling pathway." (PMID 38033576, 2023). "Differentiated colorectal cancer cells have been known to protect the stem-cell variants from chemotherapeutic toxicity, and glioma cells behaving like CSCs can produce IL-6 to promote the growth of non-CSCs." (PMID 38135951, 2023). "Furthermore, higher NLR significantly upregulates inflammatory cytokines, including IL-6 and IL-8, in colorectal cancer." (PMID 37115435, 2023). "The activation of STAT3 by IL-6/IL-11 in fibroblasts promotes the development of colorectal cancer." (PMID 38054820, 2023). "Anti-interleukin agents may have a positive effect on colorectal cancer, considering the presence of IL-1β, IL-6, and TNF-α in this neoplasia, which was also demonstrated in this prospective study." (PMID 38137862, 2023). "A small RCT showed that colorectal cancer patients who received preoperative probiotics had significantly lower levels of plasma endotoxin, D-lactic acid, interleukin-6, and C-reactive protein and higher levels of IgG and IgA immunoglobulins after colectomy compared to the control group." (PMID 36986061, 2023).
colorectal cancer (continued). "For example, in colorectal cancer cells, miR-34a is downregulated by the pro-inflammatory IL-6." (PMID 37686617, 2023). "Studies on mice with colitis-associated cancer have found that treatment with anti-IL-6 receptor antibodies reduces the incidence of cancer, suggesting that IL-6 may be a therapeutic target for colorectal cancer (CRC)." (PMID 37176567, 2023). "GVM appears to be safe and effective for alleviating CRF in patients who have completed colorectal cancer treatment, which may be related to the modulation of IL-6 and TNF-α levels." (PMID 37397368, 2023). "Similarly, the expression of cytokines TNF-α, IL-1, and IL-6 was found to be increased in drug-resistant colorectal cancer in the blood samples of each group of xenograft mouse models." (PMID 36840009, 2023). "As a weighted target, IL-6 has been extensively studied in human colorectal cancer." (PMID 38098990, 2023). "IL-6/IL-8/TNF levels after operation among colorectal cancer patients in the four groups." (PMID 35479322, 2022). "IL-6, which is a pleiotropic cytokine likely to be released in many types of cancer (e.g., colorectal cancer, advanced gastric cancer, and others), may act as an auto- or paracrine growth factor and may promote tumor invasiveness and metastasis." (PMID 36289922, 2022). "In colorectal cancer patients, the level of IL-6 is significantly and positively correlated (p = 0.004, Spearman r = 0.479) with IL-8, and similarly the IL-8 with the intake of betaine and B9 (folate) (p = 0.028, Spearman r = 0.369 and p = 0.032, Spearman r = 0.378, respectively)." (PMID 36139592, 2022). "NOVA1 enhanced IL-6/JAK2/STAT3 signaling in turn to up-regulate MMPs in colorectal cancer." (PMID 36284263, 2022). "IL-6/IL-8/TNF levels before operation among colorectal cancer patients in the four groups." (PMID 35479322, 2022). "MicroRNA-21-5p (miR-21) is highly expressed in colorectal cancer-derived sEVs, polarizes hepatic macrophages to an interleukin 6 (IL-6) producing phenotype via toll-like receptor 7 (TLR7), induces the formation of an inflammatory microenvironment, and promotes CRC liver-specific metastasis." (PMID 36552835, 2022). "Multi-factor analysis of the IL-6 level in patients with colorectal cancer." (PMID 36226059, 2022). "Several factors, including TNF, IL-6, leptin, adiponectin, and visfatin secreted by unregulated adipose tissues and adipocytes, have been shown to enhance cell proliferation, survival, migration, anti-apoptosis and angiogenesis of colorectal cancer." (PMID 34063667, 2021). "It has been suggested that IL-6 could represent a marker for evaluating the immune status of both PD-L1-negative and PD-L1-positive colorectal cancer patients, which could provide useful information for determining the therapeutic strategies." (PMID 33923292, 2021). "High levels of IL-6 in serum increase the risk of developing colorectal cancer, and this is considered an independent negative prognostic survival factor." (PMID 34944856, 2021). "IL-6 facilitates the metastatic colonization of colorectal cancer cells." (PMID 34631734, 2021). "And IL-6 responses are mediated via IL6ST-STAT3–dependent mechanisms in colorectal cancer." (PMID 33995063, 2021). "In order to reveal the potential association between tumor-derived IL-6 and macrophages, we performed that mouse macrophage RAW264.7 cells were co-cultured with mouse colorectal cancer MC38 cells / CT26 cells, after 72 h to detect MMP12 in macrophages by western blot." (PMID 34863141, 2021). "Moreover, ADAM17 has been described to be involved in EGF-R- mediated IL-6 synthesis and tumorigenesis in colorectal cancer." (PMID 34208863, 2021). "In fact, major interactions between lymphocytes mediated by IL-6 show paramount resemblance and the distinction mainly lies in the immunosuppressive influence IL-6 exerts on Mφ and T cells in times of colorectal cancer which promote the immune evasion of tumors." (PMID 33390844, 2021).